NLRP6 (NLR family pyrin domain containing 6)
Diseases named in the same sentence as NLRP6 in open-access papers (continued):
Sharing a sentence is not in itself a finding about the gene and the disease.
colitis (continued). "Reduced levels of IL-18 in the colon result in a significant decrease in epithelial cell repair, and animals deficient in NLRP6 experience both spontaneous and dextran sodium sulfate (DSS)-induced experimental colitis, which is exacerbated." (PMID 38248332, 2024). "Deficiency of NLRP6 in mouse colonic epithelial cells results in altered fecal microbiota characterized by increased colitis in NLRP6 KO mice and wild-type (WT) mice." (PMID 36876076, 2023). "In our previous study, NLRP6 was found to be involved in the process of 2′-FL alleviating DSS-induced colitis and promoting MUC2 expression in C57BL/6J mice." (PMID 36613400, 2023). "For instance, API regulates the NLRP6 signaling pathway to modulate the gut microbiota in DSS-induced colitis." (PMID 37833958, 2023). "Recently, it was discovered that taurine activates NLRP6, restoring the inflammasome-antimicrobial peptide axis and ameliorating colitis via intestinal microbes." (PMID 37189666, 2023). "Through the assembly of an inflammasome, NLRP6 was shown to prevent dextran sodium sulfate (DSS)-induced colitis by regulating IL-18 levels in colonic epithelial cells." (PMID 36613400, 2023). "NLRP6-deficient mice showed spontaneous intestinal hyperplasia, inflammatory cell recruitment, and exacerbated DSS-induced colitis." (PMID 37191444, 2023). "NLRP6 expression in intestinal epithelial cells protects against colorectal cancer and colitis via a mechanism dependent on caspase-1 mediated IL-18 production." (PMID 36761775, 2023). "For example, in Nlrp6−/− mice, Akkermansia muciniphila were shown to colonize the intestinal tract, further contributing to the development of colitis." (PMID 35954484, 2022). "A previous study showed that apigenin, a flavone that has antioxidant effect and is involved in development of various diseases, can suppress DSS induced colitis via regulating the activation of NLRP6 inflammasome." (PMID 36090968, 2022). "Different environmental communities result in variable disease susceptibility in other mouse IBD models, such as the IL-10-deficient models of acute dextran sulfate sodium (DSS) colitis 12, 13, and the Nlrp6 inflammasome-knockout colitis models." (PMID 35836813, 2022). "Similar to previous studies, we found that decreastion of NLRP6 in the colonic tissue of colitis mice." (PMID 36016685, 2022). "Baicalin ameliorates DSS-induced colitis by protecting goblet cells through activating NLRP6 inflammasomes." (PMID 36016685, 2022). "Previous studies have also shown that dextran sodium sulfate (DSS)-induced colitis mice often show a decreased number of intestinal goblet cells and an absence of intestinal mucosa as a result of the inactivation of NLRP6." (PMID 36016685, 2022). "Administration of taurine showed reduced spermine and histamine levels and induced IL‐18 production, improved microbiota composition and had a protective effect against colitis via NLRP6 inflammasome." (PMID 33682108, 2021). "Strikingly, while the intestinal community of Nlrp6-deficient mice, from which P. intestinalis was isolated, exacerbates DSS colitis in a T-cell dependent manner,32P." (PMID 32433514, 2021). "Previous studies for Nlrp6 in regulating the intestinal microbiota and response to colitis models have shown significant heterogeneity depending on the use of littermate controls." (PMID 33376129, 2021). "One such NLR, NLRP6, plays an important role in maintaining intestinal homeostasis and protecting against various intestinal diseases such as colitis and intestinal tumorigenesis." (PMID 31932628, 2020). "Specific-pathogen free NLRP6-IL-10 double knockout mice are prone to colitis resulting from expansion of the mucin degrading species Akkermansia muciniphila, mediated by the associated under-expression of IL-18194." (PMID 32550001, 2020). "One study replicated previous studies reporting a protective role for NLRP6 against colitis via regulation of healthy microbiota." (PMID 33348632, 2020).
colitis (continued). "NLRP6 deficiency in these mice results in the enrichment of A. muciniphila, which then acts as a pathobiont in the development of colitis, and highlights the ability of NLRP6 in regulating colonization of colitogenic bacteria." (PMID 33537028, 2020). "The dysbiotic microbiota observed in NLRP6 KO or ASC KO mice enhanced colitis development in WT mice." (PMID 33143375, 2020). "NLRP6-/- mice exhibit reduced IL-18 levels in intestinal epithelial cells and, interestingly, like Ogg1-/- mice were highly susceptible to DSS-induced colitis." (PMID 31935236, 2020). "In these studies, it was observed that the greatest susceptibility to the development of colitis in ASC-/-, NLRP6-/-, NLRP1-/-, NLRP3-/-, AIM2-/- or caspase-1-/- mice was related to a decrease in IL-18 levels." (PMID 32545788, 2020). "Both Nlrp6−/− and Asc−/− mice are highly susceptible to DSS-induced colitis, strongly suggesting the importance of the NLRP6 inflammasome in this disorder." (PMID 30717382, 2019). "A study showed that NLRP6, an innate immune receptor, is important for suppressing the development of spontaneous colitis in the IL10−/− mouse model of IBD." (PMID 31510015, 2019). "NLRP6 KO mice show altered microbial composition, exacerbated colitis upon chemically induced damage to the epithelial barrier, and inceased incidence of inflammation-associated colon cancer." (PMID 28955343, 2017). "Specifically, both NLRP6 and NLRP3 deficiencies are linked to exacerbation of chemical-induced colitis." (PMID 25879288, 2015). "The detrimental role of NLRP6 in the context of a bacterial IP infection appears in sharp contrast to its protective function in preventing colitis in the gut and protecting against gut infections." (PMID 25879288, 2015). "In the DSS colitis model and DSS-AOM colitis associated colon cancer murine models, several inflammasomes including NLRP3, NLRP6 and NLRC4 have been found to protect against dysplasia and hyperplasia in the colon." (PMID 26378020, 2015). "Further in vivo evidence emphasized a protective role for NLRP6 in intestinal inflammation and tumorigenesis as Nlrp6−/− mice showed high susceptibility to DSS-induced colitis and AOM–DSS-induced CRC." (PMID 25071785, 2014). "Akin to NLRP6, loss of NLRP12 in mice causes more severe colitis, in line with the role of NLRP12 as negative regulator of NF-κB and MAPK pathways." (PMID 24886810, 2014). "As observed for NLRP6, NLRP12 plays a central role in protecting against chemically induced colitis and inflammation-associated tumorigenesis." (PMID 25071778, 2014). "Accordingly, mice deficient in caspase-1, ASC, NLRP3, NLRP6, NLRP12, and NLRC4 all have increased colitis and subsequent development of colorectal cancers in gut irritant models." (PMID 24409181, 2013). "NLRP6-deficient mice develop an increased sensitivity to DSS-induced colitis and colitis-induced tumorigenesis, suggesting a protective role of NLRP6 against intestinal inflammation and inflammation-induced cancer." (PMID 24367371, 2013). "NLRP6-deficient mice show increased levels of intestinal inflammation during DSS-induced colitis and develop more severe colorectal cancer in a model of colitis-dependent tumorigenesis." (PMID 24381573, 2013). "The distinct bacterial composition of Nlrp6-knockout mice was transmissible to co-housed adult mice and cross-fostered litters and resulted in colitis-prone phenotype of recipient wild-type mice." (PMID 24409180, 2013). "In other studies focusing on the role of NLRP6 and colitis, Nlrp6−/− mice were shown to have significantly altered intestinal microbiota." (PMID 24273542, 2013). "Moreover, recent findings have underscored the emerging role of the NLRP6 inflammasome in regulating infection disease, colitis, and cancer." (PMID 39834371, 2024). "Moreover, because NLRP6 has mainly been associated with gut microbiota protection, dysregulation of NLRP activation has been associated with colitis and persistent gut infection." (PMID 38644450, 2024).
colitis (continued). "However, contradictory reports have shown that both wild-type and Nlrp6−/− littermate mice display comparable sensitivity to DSS-induced colitis." (PMID 37191444, 2023). "Fortunately, several studies have reported that natural flavonoids may protect mice from colitis by modulating an inflammasome-independent mechanism by which NLRP6 reprograms the gut microbiota." (PMID 36016685, 2022). "Based on some of the previous studies, a research group conducted a controlled trial and found that biological disorders caused by Nlrp6 and their corresponding changes do not play a major role in colitis pathogenesis." (PMID 35954484, 2022). "It has been shown that the hemolysin secreted from P. mirabilis can predispose to more severe colitis by activating NLRP3 and IL-1ß secretion while ability of A. muciniphila to degrade intestinal mucin facilitates the activation of NLRP6 in genetically susceptible individuals." (PMID 35381031, 2022). "In conclusion, Nlrp6 may affect the development of colitis or CRC by altering the composition of intestinal bacteria and the function of intestinal epithelial cells, but the same results are not obtained in the same nest control experiment." (PMID 35954484, 2022). "Considering this evidence, it is verified that the mulberry (50 mg anthocyanin/kg diet) supplementation in animals with induced colitis resulted in an increase in goblet cells and NLRP6 expression, therefore suggesting a link between mucin secretion and antimicrobial peptide production." (PMID 33920564, 2021). "In addition, NLRP6 was shown to play a host protective role in chemically-induced colitis by enhancing activity of infiltrating intestinal Ly6Chi inflammatory monocytes and neutrophils." (PMID 33036374, 2020). "By contrast, formation of other colitis-relevant inflammasomes such as AIM2, NLRP6, and NLRC4 by DSS was comparable in colons between control and UVRAGFS-expressing mice, highlighting a critical role of the NLRP3 inflammasome in UVRAGFS-associated colitis." (PMID 31831743, 2019). "This link was initially established with the finding that severe dextran sulfate sodium (DSS)-induced colitis observed in NLRP3- and NLRP6-deficient mice could be transferred to co-housed wild-type (WT) mice." (PMID 30214011, 2018). "Intriguingly, this increased colitis susceptibility resulted to be transferable to co-housed wt mice, through a colitogenic microbiota characterized by a high prevalence of Prevotellaceae and TM7 bacterial taxa, particularly present in Nlrp6 deficient mice." (PMID 29868004, 2018). "Results from these studies show that mice deficient for inflammasome components, including NLRP3, caspase-1, NLRP1, NLRP6, and NLRC4, are highly susceptible to colitis-associated colon cancer induced by AOM/DSS by displaying severe intestinal inflammation, and increased number of colon polyps." (PMID 28955343, 2017). "In addition to NLRP6, loss of NLR family members NOD1, NOD2, NLRP3, NLRC4, and NLRP12 has resulted in similar exacerbated colitis and accelerated rates of cancer." (PMID 24795727, 2014). "Like NLRC4, NLRP6 was shown to negatively regulate colitis and CAC in mice." (PMID 24273542, 2013). "The initially reported putative role of NLRP6 in modulating microbiome composition, also in the context of colitis or tumorigenesis, was contested in subsequent studies, illustrating the challenges of identifying bona fide roles of NLRP6 in a system as complex as the intestine." (PMID 41266654, 2026). "The absence of NLRP6 in experimental colitis results in a greater susceptibility to the development of the disease, determining the impairment of the intestinal microbiota, severe intestinal inflammation, and the inability to restore epithelial barrier integrity." (PMID 39684769, 2024).
colitis (continued). "Furthermore, ursodeoxycholic acid 3-sulfatecan can suppress the overexpression of inflammasomes (especially NLRP6) in colitis mice, restore colonic mucus secretion in colitis mice, and are correlated with a heightened presence of Bacteroidaceae and Clostridia_UCG-014." (PMID 38731742, 2024). "Moreover, a recent published work demonstrated that Nlrp6 was able to prevent colitis development in Il-10−/− mice by modulating the abundance of Akkermansia muciniphila which may act as a pro-inflammatory bacterium." (PMID 29868004, 2018). "NLRP6 is one of the major NLRP inflammasomes found in the intestine and liver and was discovered to protect from colitis and ensure homeostasis of intestinal and gut microbiota, and regulate intestinal antiviral innate immunity." (PMID 38644450, 2024). "NLRP6 knockout mice exhibited spontaneous intestinal hyperplasia, large recruitment of inflammatory cells, and deterioration of DSS-induced colitis." (PMID 36920176, 2023). "Recently, NLRP6 was shown to prevent the colonization of IBD-inducing bacteria, the mucolytic A. muciniphila, which can induce colitis in both specific pathogen free and germ free (GF) IL10−/− mice." (PMID 31139196, 2019). "Dysbiosis is linked to both the NLRP3 and the NLRP6 inflammasome, and mice lacking NLRP3 or NLRP6 exhibit aggravated colitis." (PMID 40796700, 2025). "NLRP6 deficient animals are enriched for A. muciniphila and display higher intestinal inflammation, and IL10-/- NLRP6 -/- mice develop spontaneous colitis in a facility where IL10-/- mice do not." (PMID 39305271, 2024). "The absence of NLRP6 results in the alteration of the gut microbiota, which leads to severe colitis." (PMID 39684769, 2024). "NLRP6 is reported to regulate MUC2 secretion in goblet cells and its crucial role was demonstrated in a previous study via the enhancement of MUC2 expression in a mouse colitis model." (PMID 36613400, 2023). "By analyzing gut microbiota phylogenetics after DSS-induced colitis of ASC-deficient mice, two studies suggested that the NLRP6 inflammasome does not shape commensal gut microbiota composition." (PMID 38146368, 2023). "Regulation of the NLRP3 inflammasome using herbal compounds can affect the development of colitis via multiple mechanisms, whereas previous studies have shown that other inflammasome forming NLRs such as NLRP1, NLRP6, NLRC4 and AIM2 are also involved in the pathogenesis of colonic inflammation." (PMID 36090968, 2022). "Previous studies have shown that a deficiency in NOD2 or NLRP6 results in a colitogenic microbiota that can exacerbate DSS-induced colitis, and the aggravated colitis phenotype exhibited by NOD2−/− or NLRP6−/− mice could be transferred to WT mice by cohousing." (PMID 35761415, 2022). "Thus, we searched the literature and found that several compounds affect the development of colitis by targeting NLRP1 and NLRP6." (PMID 36090968, 2022). "Apigenin showed a protective effect against colitis in mice via NLRP6 signalling, which still happened in the absence of caspase 1/11 or Asc, suggesting that an alternative mechanism to the classical inflammasome pathways was involved." (PMID 33682108, 2021). "Recent studies of an IL10-/- mouse model of IBD have identified NLRP6 as an important inhibitor of spontaneous colitis, whereas a lack of NLRP6 leads to the enrichment of Akkermansia muciniphila." (PMID 30971953, 2019). "Consistently, mice deficient in the antimicrobial peptide Reg3III that is regulated by NLRP6 are also not protected from colitis after treatment with apigenin." (PMID 30544686, 2018). "Their results show that NLRP6 inflammasome deficiency does not affect gut microbiota composition and DSS-induced colitis when controlling for non-genetic confounders." (PMID 28955343, 2017). "NLRP6 and NLRP3 inflammasomes are both important for resisting DSS-induced colitis." (PMID 25879288, 2015).
colitis (continued). "Moreover, NLRP6 is protective against the development of significant damage and inflammation within the colon during chemically induced DSS colitis." (PMID 25071778, 2014). "The in vivo evidence for NLRP6 inflammasome formation was provided by the demonstration that Nlrp6−/− mice have reduced serum IL-18 levels under steady-state conditions and after dextran sulfate sodium (DSS)-induced colitis compared with that of wild-type (WT) controls." (PMID 33910012, 2021). "However, in contrast to previous studies, the replication study used littermate controls and revealed that NLRP6 did not impact gut microbiota and colitis control." (PMID 33348632, 2020). "Nonetheless, in a non-infectious model, the NLRP6 inflammasome was found to be important for epithelial self-renewal, proliferation, and mucus secretion, which were essential for protection against chemical-induced colitis." (PMID 30248149, 2018). "A potential mechanism was provided by the finding that NLRP6 acts as a negative regulator of NF-κB and MAPK activation, and reduces the levels of cytokines and chemokines during infections with intestinal pathogens or epithelial barrier breach as observed during experimental models of colitis." (PMID 24381573, 2013). "NLRP6 and NLRP12 have been found to attenuate NF-kB and MAPK in models of colitis and CRC, NLRC3 has been shown to act as a negative regulator of TLR and DNA-induced cytokine production." (PMID 26378020, 2015).